CCL17 (C-C motif chemokine ligand 17)
Diseases named in the same sentence as CCL17 in open-access papers (continued):
Sharing a sentence is not in itself a finding about the gene and the disease.
tumor (continued). "Orally fed iron saturated bLf-Dox inhibited tumour development, prolonged survival, reduced Dox induced general toxicity, cardiotoxicity, neurotoxicity in TRAMP mice and upregulated serum levels of anti-cancer molecules TNF-α, IFN-γ, CCL4 and CCL17." (PMID 27576789, 2016). "Even more, CCL17/TARC and CCL22/MDC produced by both tumor and infiltrating cells in different types of cancer are able to recruit CCR4+ regulatory T and polarized Th2 cells that inhibit anti-tumor responses contributing to tumor survival." (PMID 26062132, 2015). "Gene expression analysis in pretumor mammary glands showed that all growth factors and chemokines observed to be elevated before tumor development in continuous HFD mice at 13 weeks of age (i.e., Tgfa, Ccl1, Ccl17, Ccl20, Ccl22, and Tgfb1) were elevated in LFD-HFD mammary glands at this time." (PMID 26526858, 2015). "Further, regression analysis only found weak correlation of Th17 cells with CCL22 (R = 0.385, P < 0.05), but not with CCL17 (P > 0.05), in the same tumor microenvironment." (PMID 25768730, 2015). "Using mouse models, several approaches, including the use of specific antibodies, antagonists, or siRNA, have been used to block the CCL22/CCL17 – CCR4 axis, resulting in reduction in Treg frequencies and a concomitant increase in anti-tumor activity (40, –42)." (PMID 23874342, 2013). "Therefore, mast cells-induced IL-17 increased the level of CCL17 and CCL22 in tumor microenvironment, which then chemoattracted Treg cells to tumor." (PMID 20111717, 2010). "We found that BMMC injection increased the expression of CCL17 and CCL22 in tumor microenvironment, evaluated by real time RT-PCR, which could be blunted by IL-17 neutralization or blocking MDSC migration." (PMID 20111717, 2010). "In addition, the expression of several pro-inflammatory cytokines and chemokines such as IL-1β, IL-22, TNF-α, CXCL1, CXCL2, CCL17 and CCL20 were reduced in IL-38KO mice, suggesting that IL-38 promotes tumour growth and development in cSSC through promoting an inflammatory tumour environment." (PMID 40057603, 2025). "However, there were also elevated cytokines from the Beads-FT-mA20T that could potentially contribute to the tumour-promoting responses, as represented by increased levels of CXCL16, CXCL2 and CCL17 (See Section 4)." (PMID 40361460, 2025). "In addition, we show that the mechanism by which tumors facilitate the involvement of non-natural CD8+ T cells and enhance tumor resistance following 6 Gy treatment is through the release of CCL17." (PMID 39877375, 2024). "However, CCL17 is also expressed specifically by neutrophils and macrophages and plays a significant role in the alternative cross-priming of dendritic cells (DCs), enabling them to trigger CD8+ T lymphocyte responses against tumor antigens." (PMID 37762335, 2023). "CC chemokine receptor 4 (CCR4), with two ligands, CCL17 and CCL22, is a key chemokine receptor selectively expressed on normal T cells that mediates the entry of regulatory T cells into the tumor microenvironment, and it is mainly expressed in tumor-infiltrated Treg cells." (PMID 36992198, 2023). "In addition, treatment with clodronate in advanced tumor stages has been shown to effectively reduce M2 phenotypic markers, including IL-10, TGF-β, CCL17, and MCP-1.104Fusobacterium nucleatum is a type of bacteria that does not require oxygen to survive and has a rod-like shape." (PMID 37943609, 2023). "From this we could postulate that CCL17, CXCL1 and CCL2 act early and in a similar way to indirectly help tumour growth, possibly by upregulating CXCL10 production and myeloid cell expansion, which act more directly on tumour growth." (PMID 35226704, 2022).
tumor (continued). "Among them IL-1, IL-6, epidermal growth factor (EGF) help tumor cells survive, VEGF and IL-8 promote angiogenesis, M2 macrophages, and MDSCs antagonize inflammatory responses, IL-10, TGF-β, C-C motif chemokine ligand (CCL17) inhibits tumor immune function, and TGF-β and MMP promote tumor metastasis." (PMID 36686745, 2022). "Notably, since CCL17 and CCL22 are ligands of CCR4, the major chemokine receptor expressed in CTCL cells, the production of these chemokines from TAMs could result in tumor formation in mycosis fungoides in the tumor stage." (PMID 35409404, 2022). "Ddx5 was increased in the whole skin lesions of MC903- or IMQ-treated Cd93–/– mice compared with their wild-type counterparts, along with fewer plaques on the ears or dorsal skin and reduced expression of Il4, Il13, Ccl11, Ccl17 and Ccl22 or Cxcl1, Cxcl2, Ccl20, Il23, Il17a and Il36γ." (PMID 36271146, 2022). "An early study to arm T cells with tumour‐specific chemokine receptors was done to target Hodgkin tumour cells, for which T cells were engineered to produce high thymus‐ and activation‐regulated chemokine/CC chemokine ligand 17 (TARC/CCL17) and macrophage‐derived chemokine." (PMID 36495108, 2022). "After Tregs depletion, tumor formation was attenuated in CCL17 TG mice compared with that in WT mice depleted of Tregs, suggesting that the decrease in MDSCs in a high level of CCL17 may positively contribute to tumor immunity in the absence of Tregs." (PMID 33670758, 2021). "The anti-tumor “N1” phenotype exhibited increased tumor cytotoxicity, elevated expression of CXCL13, CCL3, CCL6, CXCL10, TNFα and ICAM-1 and low ARG1 content, while the pro-tumor “N2” neutrophils expressed high levels of ARG1, MMP9, VEGF and several cytokines, including CCL2, CCL5, CCL17 and CXCL4." (PMID 34572138, 2021). "Analysis of the total thymic cell population suggests insignificant changes in CCL17 (ligand for CCR4) and a modest decrease in CCL19 (ligands for CCR7) at day 25 but a drastic reduction in expression of CCL21 (ligands for CCR7) when comparing thymi harvested from tumor-bearing vs. control mice." (PMID 32582141, 2020). "Moreover, CCL17 and CCL22 can also attract CCR4-expressing Treg cells, which may further suppress cytotoxic T-cells and prevent tumor immunosurveillance of the ATL cells." (PMID 29915722, 2018). "More importantly, Fe-bLf Dox was capable of inducing greater expression of anti-tumour and macrophage homing chemokines such as GM-CSF (1.7 fold), CCL11 (1.8 fold), IL-1ra (1.3 fold), IL-23 (1.5 fold), CCL12 (1.8 fold), CCL4 (1.5 fold) and CCL17 (1.7 fold), than Dox injections." (PMID 27576789, 2016). "Furthermore, there is no definitive evidence to determine whether CCL17 might be an independent target for cancer therapy or whether it might cooperate with other effective immune checkpoint inhibitors to enhance the anti-tumor effect in HCC." (PMID 38914802, 2024). "Then, the TANs that are distributed in the HCC stroma, but not in tumor cells or adjacent non-tumor hepatocytes recruit macrophages and Treg cells into HCC by secreting CCL2 and CCL17 to promote the HCC progression." (PMID 33224886, 2020). "On the contrary, we did not found increased expression of CCL17 and CCL20, the two specific ligands of CCR4, in tumor tissue." (PMID 25768730, 2015). "Ligands for CD194 (e.g., CCL17 or CCL22) were in contrast to IL-6 and TGF-β not highly expressed in the tumor tissue, altogether indicating a conversion from CD8+ rather than a tumor-directed migration as the cause for the observed infiltration." (PMID 22110523, 2011). "Ligands for CCR4 (e.g., CCL17 and/or CCL22) were in contrast to IL-6 and TGF-β not highly expressed in the tumor tissue, altogether indicating a conversion from CD8+ Tconvs rather than a tumor directed migration as the cause for the observed infiltration." (PMID 24212779, 2011).
tumor (continued). "The results showed that CCL17 and CD3G (CD4/CD8+ T cell marker molecule), CD4 (CD4+ T cell marker molecule), and CD79B (naive B-cell marker molecule) were expressed to some extent in tumor tissues of three LUAD patients without dysregulation." (PMID 35321241, 2022). "Those chemokines were preferably expressed by neutrophils throughout the tumor stroma but not by tumor cells or by the adjacent non-malignant tissues, while patients whose tumors had lower levels of CCL2+ or CCL17+ cells had longer survival times than those with higher numbers of these cells." (PMID 34200529, 2021). "The quantitative PCR results were consistent with the transcriptome results, showing that the expression of CCL2, CCL3, CCL5, and CXCL9, but not CCL17 or CCL22, was markedly higher in 1.5 mg/kg AAGL-treated tumor-bearing mouse livers than in those of control mice." (PMID 33710817, 2021). "However, the expression of several anti-inflammatory cytokines, such as CCL17, CCL22, IL-10, and TGF-β, and the M2 marker ARG1, was not significantly changed; these results were consistent with the transcriptome data in H22 tumor-bearing mouse liver tissue." (PMID 33710817, 2021). "Furthermore, exploration of the correlation between CCL17 expression and key pathways in NSCLC patients revealed a positive correlation with pro-inflammatory pathways and a significant negative correlation with tumor proliferation pathways." (PMID 39877375, 2024).
infection (68 papers, 2008 to 2025). The state of being infected such as from the introduction of a foreign agent such as serum, vaccine, antigenic substance or organism. "However, we observed only a small (i.e. fourfold) reduction in bacterial load in mLN 1 day after oral infection of CCL17‐deficient mice with STM." (PMID 33945673, 2021). "It therefore appears that CCL11 and CCL17 reach their highest levels during the early phase of infection, acting as rapid attractants for eosinophils to the site of inflammation." (PMID 40918106, 2025). "Compared to the H99 strain infection, Cxcl1, which can recruit and activate neutrophils, and Ccl17, secreted by M2 macrophages to act on Th2 cells, showed a gradually increasing expression level in the lungs of mice infected with the cdh1Δ mutant strain." (PMID 39728387, 2024). "We found that patent schistosome infection led to more dramatic airway cytokine changes than pre-patent infection, with a clear trend for an increase in airway levels of Ym-1, Relmα and CCL17." (PMID 37012228, 2023). "CCL17 levels were also considered as predictive markers for the differentiation of mild/moderate cases from severe/critical COVID-19 infections, with higher CCL17 levels in mild/moderate cases during early infection." (PMID 34802072, 2022). "We demonstrate that the frequency of CCL17+ cells increases after STM infection and that STM+ DCs contain a higher proportion of CCL17+ cells than noninfected DCs." (PMID 33945673, 2021). "In this study, we aimed to investigate the role of CCL17 during the early phase of infection, including bacterial spreading from the intestine to the draining LN." (PMID 33945673, 2021). "Although CCL17 is strongly expressed only at 7 days post-infection and we cannot exclude the possibility that other mediators cooperate in DC migration, the data suggest the involvement of CCR4 in the recruitment of these cells." (PMID 31611578, 2019). "The production of CCL17 protein was confirmed by immunohistochemistry, which showed intense staining of this chemokine in pancreatic duct cells 7 days after infection." (PMID 31611578, 2019). "Amongst cytokines, the genes for Cxcl9, Cxcl10, Cxcl13, Il-1β, Il-6, Tnf, Tnfsf10, IFN-γ, Ccl2, Ccl4, Ccl7, Ccl17, and Mif were highly up-regulated (ranging from 2- to 405-fold, p ≤ 0.05), whereas Cxcl12 and Cxcl14 were down-regulated during in vivo infection." (PMID 30857242, 2019). "Accordingly, we found increased RNA abundance of Arg1, Socs1, Sra1, Saa1, Ciita, Marco, Mgl2, Cd209d, Cd209e, Cd209f, Ccl1, Ccl11, Ccl17, Ccl19, Ccl20, Ccl22, and Ccl24 genes in Stat2−/− mice when compared to WT mice during super-infection." (PMID 30337919, 2018). "At pre-treatment, the chemokines CCL5, CCL11, and CCL17 were readily detected in all infection groups and the frequencies of responders were similar to the egg-negative individuals." (PMID 30619332, 2018). "In fact, several of the cytokines seen here are the same neutrophil chemokines (Cxcl5, Ccl4, Cxcl1) and T-cell chemokines (Cccl5, Cxcl10, Ccl17) that were highlighted in the infection effect analysis." (PMID 30134832, 2018). "Because CCR4 deficiency increases susceptibility in the chronic phase of infection, we next assessed the gene expression of CCR4 and its ligands CCL17 and CCL22." (PMID 30584243, 2018). "Levels of CCL17/TARC in BAL were however significantly elevated in RV infected Tbet-/- vs. w/t control mice on day 7 post-infection." (PMID 27683080, 2016). "For instance, the most differentially regulated chicken gene in comparisons of infection with WT versus ROP16-KO Type I parasites or Type III versus Type II parasites is CCL17." (PMID 22022607, 2011). "Upregulation of the expression of adiponectin, CCL19, and CCL17 genes following infection with either of the ILTV strains in the TOCs in this study indicates that gG may not influence the transcription of these genes locally in the trachea." (PMID 39804092, 2025).
infection (continued). "Along the course of infection, there was a reduction in the expression of M1 markers like Nos2, Cd40,Cd86, Tnfa, Nfkb2, Il6 and a corresponding increase in the expression of the M2 markers such as Arg1, Ccl17, Cd206, IL4ra with an exception of Tgfb." (PMID 39693143, 2024). "Chemokine measurement 6 hours post bacterial infection showed similar trends in some cytokines, but also highlighted the importance of cytokine kinetics within infection, as multiple chemokines were altered only at early time points, including CCL17, CCL22, IL-6, and CXCL5." (PMID 39178311, 2024). "Our first multiple regression model confirmed the results from the univariable immunological analysis and showed a positive association of CCL17 and CCL3 higher responders and a high frequency of IL-17 responders with S. mansoni active infection in the study population." (PMID 33777015, 2021). "Nevertheless, deficiency in CCL17 resulted only in a moderate reduction of the bacterial burden in the mLN but not in PP or systemic organs one day after STM infection." (PMID 33945673, 2021). "Confirming the observations made above, infection with all three L. major induces (cluster 1) neutrophil recruitment, myeloid activation, and production of cytokines/chemokines (e.g. Trem1, Trem3, C5ar1, Ltf, Ptgs2, Ccl2, Ccl12, Ccl17, etc.)." (PMID 34972189, 2021). "In the present work, we have shown that intraperitoneal infection of mice with CVB5 induced pancreatic duct cells to produce the chemokine CCL17, whereas the expression of its receptor, CCR4, was increased in the pancreas, and CCR4+ cells accumulated in the PLN." (PMID 31611578, 2019). "Next, we found increased mRNA expression and activity levels of Arg1, mRNA expression of Fizz, Chi3l3, Cd209d, Cd209e, Mrc2 (Cd206), Marco, Il13, Saa1 (Serum amyloid A1 protein), Ccl17, Ccl19, Ccl20, Ccl22, and Ccl24 in Stat2−/− mice compared to WT mice during super-infection." (PMID 30337919, 2018). "In the context of macrophages infection, GRA18 induces the expression of a specific set of genes commonly associated with an anti-inflammatory response that includes those encoding chemokines CCL17 and CCL22." (PMID 30320549, 2018). "Interestingly, while JMJD3 was found to negatively regulate few of the mycobacteria-responsive M1 markers of macrophages viz., Il12, Il1b and Cxcl2, the expression of M2 markers like Arg1, Mrc1, Il10, Tgfb, Ccl17 and Ccl2 on infection were JMJD3-dependent." (PMID 27532872, 2016). "Our data reveal a previously unknown mechanism by which cells important for the resolution of infection are able to migrate to the site and perform their functions, and our data point to CCL17 and CCR4 as potential targets for the treatment of viral pancreatitis." (PMID 31611578, 2019). "The expression levels of CXCL1, CCL17, and CCL20 were significantly upregulated 21 days after infection with the cdh1Δ mutant strain, indicating a pronounced activation of lung tissue recruitment of neutrophils and enhanced Th2 and Th17 immune responses." (PMID 39728387, 2024). "In our study on the early infection phase of FHV-1, the upregulation of CCL17, CCL20, and CXCL10 among these cytokines and chemokines, as well as that of TNF were observed, while there were no significant changes in IFNs." (PMID 39591303, 2024). "The E. multilocularis antigen (EmAg) inducible cellular productions of MCP1(CCL13), TARC(CCL17) and PARC(CCL18) were lowest in patients with cured AE and infection-free controls, while the EmAg inducible cellular production of IFN-γ increased after cure." (PMID 35108275, 2022). "The CC chemokines TARC(CCL17), PARC(CCL18) and LARC(CCL20) were measured in serum samples of AE patients and infection-free controls." (PMID 35108275, 2022). "The activation regulated chemokines TARC(CCL17), and PARC(CCL18) were produced lowest by PBMC from cured AE patients and infection-free controls (for TARC p<0.01 versus controls) (Part C)." (PMID 35108275, 2022).